EGFR (epidermal growth factor receptor)
Diseases named in the same sentence as EGFR in open-access papers (continued):
Sharing a sentence is not in itself a finding about the gene and the disease.
tumor (continued). "The COX-2 and EGFR pathways mutually enhance their pro-tumorigenic effects in different tumor types and we have previously shown that the combined treatment of the anti-EGFR drug AEE788 and the specific COX-2 inhibitor celecoxib demonstrated enhanced anti-tumoral efficacy in CRC cells." (PMID 28423516, 2017). "EGFR in the primary tumours were first detected and it is overexpressed in the tumour tissues." (PMID 28393839, 2017). "However, EGFR 19-del was exclusively detected in the tumor tissue of NO12 patient by NGS, while standard molecular testing (ARMS) is negative." (PMID 28380452, 2017). "However, despite initial efficacy, all the patients will eventually develop resistance to EGFR TKIs resulting in tumor progression." (PMID 29285237, 2017). "What are the levels of EGFR activity in tumor cells in vivo?" (PMID 29268862, 2017). "Since an elevated human-cancer occurrence is associated with an aberrant receptor function for the epidermal growth factor receptor (EGFR), molecular docking studies were used to examine preferential metabolite interactions/binding and probe the mode-of-action for metabolite-anti tumor activity." (PMID 28635645, 2017). "Most subjects had loss or decreased expression of EGFRvIII in tumors despite no change in the degree of EGFR amplification or other tumor mutations." (PMID 29312333, 2017). "A shared EGFR R222C missense mutation was present in both the primary and recurrent tumors, indicating that alteration of the RTK pathway is nonetheless conserved in the recurrent tumor." (PMID 29084603, 2017). "It is hypothesized that elevated VEGF, which promotes tumor angiogenesis, induces acquired resistance to EGFR treatment." (PMID 28288572, 2017). "The hypothesis behind the use of HER1-based vaccine is to harness the immune system against EGFR expressing tumor cells with minimal toxicity." (PMID 28539888, 2017). "We have addressed this difficulty by using a unique liposome-based delivery system with an EGFR targeting peptide displayed at the surface of the lipopolyplex, achieving for the first time tumour cell-specific uptake and expression of the EGFR biosensor in vivo." (PMID 28166195, 2017). "Therefore, in the future, we will modify and conjugate some tumor antigen specific ligands, such as EGFR antibody and RGD peptide, to the surface of GNs for an enhanced active targeting." (PMID 28423503, 2017). "Present data are in agreement with previous observations from our group indicating that the engagement of the Epidermal Growth Factor Receptor (EGFR) by AvidinOX-bound biotinylated Cetuximab or Panitumumab, leads to potent tumor inhibition both in vitro and in animal models." (PMID 28186982, 2017). "In total, 49 patients (43.0%) were both tumor-tissue and plasma cfDNA EGFR M+; 31 patients (27.2%) were tumor-tissue EGFR M+ but plasma cfDNA EGFR M-; 3 patients (2.6%) were tumor-tissue EGFR M- but plasma cfDNA EGFR M+; and 31 patients (27.2%) were both tumor-tissue and plasma cfDNA EGFR M-." (PMID 28052016, 2017). "The trial was undertaken in an era before widespread testing for activating mutations of EGFR and ALK, histological differentiation and maintenance chemotherapy were standard practice and the newly introduced immune-checkpoint inhibitor for tumours with high PD-L1 expression." (PMID 28780466, 2017). "In addition to antitumor effects, we provide novel evidence that miR-206 can inhibit tumor resistance by suppressing the c-MET/EGFR-BCRP axis." (PMID 29291022, 2017). "The tumor clones of increased EGFR copy number could potentially have been eliminated during the process of recurrence." (PMID 28854970, 2017). "However, the effect of EGFR overexpression on tumor growth was dramatically attenuated when miR-338-3p was inhibited or EYA2 was knocked down." (PMID 28703807, 2017).
tumor (continued). "Encouraging results showing anti-tumor efficacy when the inhibition of EGFR is combined with the targeting of phosphatidylinositol 3-kinase (PI3K) indicate the necessity to inhibit alternative pathways triggered by EGFR inactivation." (PMID 28446239, 2017). "We searched for additional molecular alterations in other genes as possible driver of tumor progression, in the subgroup of cases (N = 6) with complex EGFRm or with rare EGFR mutations not responsive to first-line EGFR TKIs." (PMID 28427238, 2017). "Moreover, epidermal growth factor receptor (EGFR) has been attributed to a sustaining role of tumor cell intravasation and dissemination." (PMID 28785589, 2017). "Analyses of tumor samples from NSCLC patients with acquired EGFR TKI resistance could reveal molecular mechanisms of resistance." (PMID 28969097, 2017). "Our (unpublished) data showed that icotinib could be useful in the inhibition of EGFR activity in A549 cells expressed EGFR protein in tumor xenografts." (PMID 27852073, 2017). "Immunohistochemical analysis showed that 50 patient tumor samples (71.4%) had high EGFR expression." (PMID 28881608, 2017). "Initial EGFR mutational status reported in this work were characterized in non-synchronously collected diagnostic tumor tissue samples." (PMID 28829811, 2017). "Opportunity exists to explore methods to enhance lesional absorbed dose such as the concomitant use of drug therapy which may radiosensitize tumours (e.g. chemotherapy +/− anti-EGFR monoclonal antibodies or bevacizumab)." (PMID 28536968, 2017). "In addition, the functions of multiple cathepsins as sheddases that cleave extracellular receptors, such as plexins and EGFR, were recently uncovered, further supporting their tumor suppressing roles." (PMID 29088746, 2017). "Therefore, EGF-dose-dependence of the pY1068/EGFR ratio measured using a 10-min stimulation of cells in vitro was employed as a linear standard to estimate ligand concentrations in vivo in tumor xenografts." (PMID 29268862, 2017). "However, development of tumor resistance remains a serious problem that necessitates ongoing development of novel EGFR inhibitors." (PMID 28915593, 2017). "This study was to explore the relevance between serum tumor markers and treatment of EGFR-TKIs." (PMID 28935011, 2017). "Serial ctDNA measurements could complement routine imaging-based assessments in evaluation of disease bulk, response to chemotherapeutic agents, re-challenge with anti-EGFR therapy, and detection of residual disease after surgical resection of the tumor." (PMID 28945877, 2017). "The epidermal growth factor receptor (EGFR) plays a very important role in tumor progression because binding of its ligands initiates a cascade of intracellular phosphorylations that ultimately triggers genes associated with cell proliferation, survival, or invasion." (PMID 28352231, 2017). "The epidermal growth factor receptor (EGFR) is part of a complex series of cellular signaling pathways that lead to increased cell proliferation, motility, survival, and angiogenesis, all of which can lead to tumor growth and progression." (PMID 27853997, 2017). "In view of the fact that miR-107-5p is significantly down regulated in NSCLC, moreover, we hypothesized that miR-107-5p may play an important role in tumorigenesis and tumor development in NSCLC by regulating EGFR." (PMID 28915650, 2017). "Therefore, there is a significant association between the presence in the nucleus of tumor cells of FOXM1 transcription factor and patient response to anti-EGFR treatment with cetuximab." (PMID 28423516, 2017).
tumor (continued). "Compared with tumor-tissue-based detection, the sensitivity of ddPCR for detecting plasma cfDNA tyrosine kinase inhibitor (TKI)-sensitizing EGFR mutations was 61.3%, the specificity was 96.7%, and the consistency rate was 81.4% (?=0.605, 95% confidence interval: 0.501-0.706, p <0.0001)." (PMID 28052016, 2017). "To take the next step in the translation of this novel theranostic NIS gene strategy from laboratory scale to the clinical situation, in the current paper, we applied the NIS pDNA polyplexes in a high EGFR-expressing tumor model of metastatic colorectal cancer." (PMID 29190908, 2017). "Further, SsaI synergistically enhanced the anti-tumor effects of EGFR inhibitor on EOC cells." (PMID 28423672, 2017). "Mutant EGFR was identified as a potential target due to its prominence in tumor cells." (PMID 28611939, 2017). "Loss of DEP-1 function in cancer cells could simultaneously activate cell proliferation via hyperactive EGFR signaling and increase tumor cell mobility and invasion by reducing integrin-mediated cell adhesion." (PMID 28135265, 2017). "However, after a certain period of drug exposure, tumor cells gradually become insensitive to EGFR-TKIs, ultimately surviving following exposure to chemotherapy drugs." (PMID 28978341, 2017). "In addition, resistance to an anti-EGFR antibody was also induced in tumor cells by the co-culture of cancer cells and HGF-producing lung fibroblasts." (PMID 28619066, 2017). "Treatment with ChMS-1 antibody moderately inhibited EGFR phosphorylation in the tumour xenograft." (PMID 28642617, 2017). "Tumor lysates were additionally evaluated for EGFR phosphorylation." (PMID 29230082, 2017). "However, the effect of sequential treatment with various anti-EGFR agents on tumor evolution and drug resistance in EGFR-mutant NSCLC remains to be determined." (PMID 28416737, 2017). "However, since VM contributes to feed the tumor it is likely that the drastic anti-proliferative effect observed is not only a direct consequence of CL4-mediated inhibition of EGFR activation, but also achieved through the reduction of VM." (PMID 28425453, 2017). "After stimulating with EGF ligand (20 ng ml−1) FLCN null cells (FTC-133 FLCN−/−) and cells expressing tumour-associated mutant forms of FLCN (FTC-133 K508R and FTC-133 dF157) have increased levels of phosphorylated EGFR (pEGFR) compared to cells expressing FLCN WT." (PMID 28656962, 2017). "It is specifically lethal to EGFR highly expression tumor cell lines in vitro." (PMID 28445134, 2017). "Analysis of EGFR mutations in tumor tissue is not always possible due to the invasive nature of biopsies, inaccessibility of tumor location, or low quantity and quality of the tissue samples." (PMID 29029416, 2017). "Besides, ND-PTX-Cet markedly decreased tumor size in the xenograft EGFR-expressed human CRC tumors of nude mice." (PMID 28852020, 2017). "Besides, PKM2 can combine with histone H3 and be adsorbed to T11-level phosphate group after EGFR activation, which promotes the proliferation of tumor cells." (PMID 29299177, 2017). "In addition, REP1 knockdown showed antitumor effects in a human tumor xenograft mouse model with EGFR downregulation." (PMID 28230863, 2017). "We examined the direct effect of EGFR/HER2 inhibition on the cytokines release of tumor cell lines." (PMID 28969039, 2017). "Similar to tumor growth, hyperplastic synovium of RA also expresses EGFR and its ligands." (PMID 28700691, 2017). "Rosenthal and collaborators (2015) described the results of the first-in-human clinical trial using cetuximab conjugated to IRDye® 800CW to guide the surgery of head and neck squamous cell carcinoma and the fluorescence was correlated to EGFR expression of the tumor." (PMID 27379987, 2017).
tumor (continued). "In vivo imaging with MRI- fluorescence molecular tomography (MRI-FMT) of mice injected with IRDye 8000CW labeled EGF, showed a 100% sensitivity and specificity in distinguishing mice with EGFR (+) tumor cell lines from EGRF (−) tumor cell lines or control mice." (PMID 27878374, 2017). "As with Yki, combining EGFR with other factors can drive tumor formation." (PMID 28754838, 2017). "Only a few reports have described residual tumor resection after EGFR-TKI treatment." (PMID 29169381, 2017). "This could further advance the development of specific EGFR-targeting antibodies, such as can225IgG, for dog tumor patients." (PMID 29137329, 2017). "In various tumor entities, both the overexpression of receptors and tyrosine kinases such as EGFR, HER2/neu and IGF-1R, the inhibition of tumor cell growth by kinase inhibitors and synergistic effects of combining these inhibitors with conventional chemotherapy were shown." (PMID 28591197, 2017). "This unique feature may result in better target engagement for theliatinib compared to erlotinib or gefitinib, leading to stronger anti-tumor activity in tumors with wild type EGFR activation due to gene amplification or protein overexpression." (PMID 28881608, 2017). "Most of these patients were stage IV (86.7%) and tumor tissues are not sufficient for EGFR mutation analysis." (PMID 28107191, 2017). "Furthermore, genomic profiling shows that cell cycle regulators are altered in the majority of EGFR-amplified tumours and a combination of cyclin-dependent kinase 4/6 (CDK4/6) and EGFR inhibitors prevents the emergence of resistance in vitro and in vivo." (PMID 28059068, 2017). "A greater proportion of tumor rim was EGFR positive (58%) compared to 46% of tumor centers." (PMID 28456115, 2017). "One such possibility may be the interaction of antagonists with EGFR expression on healthy cells in the tumor microenvironment, such as tumor-intrinsic fibroblasts, or on cells of the immune system." (PMID 28970798, 2017). "Large group of patients without PD-L1 expression on tumor cells was identified among patients with common EGFR mutations and ALK rearrangement." (PMID 28969070, 2017). "Contemporary precision medicine initiatives that pair patient tumor characteristics with the optimal therapy type may maximize the use of agents targeting EGFR in the treatment of NSCLC." (PMID 28938541, 2017). "Furthermore, aberrant activation or gene mutations of other targets such as PI3K and FGFR diminished the anti-tumor activity of the EGFR TKIs, especially, theliatinib." (PMID 28881608, 2017). "In IHC assay using SP142 antibody, four patients with common EGFR gene mutations presented no expression of PD-L1, one of whom (with deletion in exon 19) showed PD-L1 expression on 10% of tumor cells (with 22C3 antibody)." (PMID 28969070, 2017). "Similarly, activated EGFR induces translocation of PKM2 into the nucleus where it interacts with other transcription factors promoting tumor growth." (PMID 29270389, 2017). "This provides a potential mechanism whereby anti-EGFR therapeutics that inhibit EGFR trafficking and/or signaling could potentiate the effects of X-rays and chemotherapeutics aimed at inducing tumor cell death through DNA damage." (PMID 28646091, 2017). "A potential clinical application of our observations could be the development of a test for patient responsiveness to EGFR-TKI treatment using non-invasive serum tumor markers." (PMID 28705152, 2017). "First, we demonstrated that ddPCR assays could achieve a detection sensitivity of 0.02% for mutant EGFR L858R, ex19del, and T790M, using tumor cells and normal human blood." (PMID 28061461, 2017). "In addition, treatment with EGFR-specific CAR-NK-92 cells significantly suppressed tumor growth compared with the Ctrl-NK-92 cells." (PMID 29423418, 2017). "In addition, HCaRG secreted form renal epithelial cells inhibited tumor cell proliferation and suppressed the expression of ErbB receptors (EGFR and ErbB3)." (PMID 29050225, 2017).
tumor (continued). "For these studies we hypothesize that tumor phenotype strongly influences tumor progression and cases with strong epithelial character would benefit the most from strategies targeting EGFR." (PMID 28938541, 2017). "Consistent with the hypothesis of the essential role of ERK1/2 signaling, inhibition of this pathway suppressed the EGFR-dependent growth of tumor xenografts of MDA-MB-468 and other cells." (PMID 29268862, 2017). "We firstly explored whether the combination of MWA at primary tumor sites and EGFR-TKIs could improve PFS when compared with EGFR-TKIs alone for advanced NSCLC with EGFR-sensitive mutations." (PMID 28915624, 2017). "The studies on tumor locations is especially important as recent data emerges to indicate that the location of tumors is a prognostic marker for survival, as well as a predictive marker for response to EGFR inhibitor therapy." (PMID 29237405, 2017). "We speculate that high-dose icotinib could improve tumor vascular hemodynamics thereby increasing the effect of cytotoxic drugs on wild-type EGFR NSCLC cell xenografts." (PMID 27852073, 2017). "Theoretically, the combined inhibition of two distinct but related pathways, such as the VEGFR and the EGFR or the PD-1/PD-L1, could produce a more sustained suppression of cancer-related angiogenesis and tumor growth." (PMID 28881856, 2017). "However a significant fraction of wild-type tumours remain unresponsive to cetuximab targeting EGFR (refs 8, 9) thus requiring novel biomarkers predicting treatment outcomes." (PMID 28186126, 2017). "Although the exact mechanism is still unknown, the general trend is that PDT is able to inhibit and/or degrade EGFR, thereby deterring tumor growth and inducing apoptosis." (PMID 27803950, 2017). "We then compared the TGI induced by these affinity-modulated monospecific EGFR/NMGC DuetMabs with the TGI mediated by their corresponding bispecific EGFR/HER2 DuetMab counterparts in single-flank tumor xenografts carrying only the double-positive NCI-H358 tumors." (PMID 28067257, 2017). "Their results indicated that engaging the IGF-1/IGF-1R system might enable tumor cells to escape anti-EGFR-mediated treatment as a consequence of IGF-1-driven stimulation of the PI3K–Akt pathway." (PMID 28423026, 2017). "In addition, CK2 knockdown alone or in combination with EGFR knockdown increased mouse survival and necrosis in the tumor tissue of GBM xenograft mouse models." (PMID 28134850, 2017). "Targeting EGFR with the inhibitory antibody cetuximab may affect the motile and invasive behavior of tumor cells." (PMID 29237412, 2017). "Thus, even ‘off-the-shelf' nanomedicines, such as Doxil, can be targeted to EGFR+ TNBC tumours by this approach." (PMID 28593948, 2017). "Moreover, a recent preclinical study in animal models demonstrated superior penetration of the BBB with osimertinib than gefitinib or afatinib and sustained tumor regression in an EGFR-mutant mouse brain metastasis model." (PMID 28993799, 2017). "Thirty‐six EGFR and sixteen KRAS mutations were found in tumor tissues of 168 patients." (PMID 28382702, 2017). "Thus, the frequency of tumor-tissue EGFR M- and plasma cfDNA EGFR M+ patients is 4.0% (155/3834), which is higher than the frequencies of tumor tissue rare mutations such as ROS1, RET, BRAF, etc." (PMID 28052016, 2017). "The clinical sensitivity, specificity, positive prediction value (PPV), and negative prediction value (NPV) of ADx-SuperARMS EGFR assay were calculated by using EGFR mutation status in tumor tissue as standard reference." (PMID 28829813, 2017). "Moreover, EGFR expression outside the tumor compartment was observed in the normal epithelium in all cases." (PMID 28841839, 2017). "Those previous findings indicate that tumor cells with EGFR amplification are invasive." (PMID 28854970, 2017).